ATG12 (autophagy related 12)
Diseases named in the same sentence as ATG12 in open-access papers (continued):
Sharing a sentence is not in itself a finding about the gene and the disease.
cyst (2 papers, 2016 to 2023). A sac-like closed membranous structure that may be empty or contain fluid or amorphous material. "Similarly, knockdown of atg12 in the protozoan parasite Acanthamoeba castellanii resulted in the inhibition of cyst formation." (PMID 27309377, 2016). "Atg12 together with Atg16 constituted another UBL system related to autophagy and the knockdown of Atg12 or Atg16 showed ultrastructural changes of the cyst." (PMID 37089530, 2023). "The main features of Atg12-knockdown cells are the absence of maturation of cyst wall, decrease in autophagic structures, and vacuolization." (PMID 37089530, 2023).
cystic fibrosis (2 papers, 2020). Autosomal recessive disorder caused by pathogenic variants in the CFTR gene (cystic fibrosis transmembrane conductance regulator), which encodes a chloride and bicarbonate channel expressed in epithelial cells, and follow the diagnosis criteria. "Furthermore, the activation of autophagy induced by epigallocatechin-3-gallate restricted the B.cenocepacia replication and subsequently ameliorated cystic fibrosis by suppressing the methylation of Atg12 promoter and increasing Atg12 expression." (PMID 32724454, 2020). "Similarly, in macrophages cells of cystic fibrosis mice, EGCG (administered intratracheally for three days with 25 mg/kg) restored Atg12 gene expression, improving autophagy in such a disease, where autophagic process highly impaired." (PMID 31979082, 2020).
dementia (2 papers, 2019 to 2024). Loss of intellectual abilities interfering with an individual's social and occupational functions. "Plasma ATG12 and ATG5 levels showed significant group difference between control and patients with dementia and MCI by Kruskal-Wallis test (p = 0.019, p = 0.023, respectively)." (PMID 30894637, 2019). "Since altered proteolytic cleavage of L1 was observed in patients with Alzheimer’s disease and other dementias, interactions of L1 with LC3, ATG12, and p62 may be altered in these patients." (PMID 39409157, 2024). "Next, to clarify whether ATG5 and ATG12 levels are related to clinically overt dementia, we examined ATG5 and ATG12 plasma levels in mild cognitive impairment (MCI) and dementia patients as well as in control subjects without dementia." (PMID 30894637, 2019).
myocardial infarction (2 papers, 2018 to 2023). Gross necrosis of the myocardium, as a result of interruption of the blood supply to the area, as in coronary thrombosis. "TUNEL and Masson staining presented that over-expression of ATG12 slightly increased the area of myocardial infarction and cardiac apoptosis, and Ad-ATG12 administration abrogated the inhibition effect of 3AB on infarct area and myocardial apoptosis." (PMID 30323296, 2018).
neuroblastoma (2 papers, 2016 to 2021). Neuroblastoma (NB) is the most common solid, extracranial childhood tumor. "The expression of LC3B and ATG3, ATG5, ATG7, ATG12 proteins was also markedly up-regulated after BIX01294 treatment in neuroblastoma cells." (PMID 27934912, 2016).
Obesity (2 papers, 2021 to 2024). Accumulation of substantial excess body fat. "Atg12 transcripts were consistently downregulated by CR; in females the effect was modest, while in males, Obesity significantly elevated Atg12 mRNA, while CR attenuated levels in both diet groups." (PMID 38166559, 2024).
Salmonella Infections (2 papers, 2014 to 2018). Infections with bacteria of the genus SALMONELLA. "To differentiate between the FIP200 and WIPI2 binding requirements for Atg12–5-16L1 recruitment to the phagophore during Salmonella infection, we transfected Atg16L1Δ/Δ MEFs with WT FLAG-Atg16L1, ERER (WIPI2-binding mutant), or DRDR (FIP200-binding mutant)." (PMID 24954904, 2014). "Salmonella infection down-regulated the expression of the following protein biomarkers of autophagy (a catabolic process for stress adaptation of cellular components): Beclin-1, Atg5, Atg12, Atg16, LC3-I and LC3-II." (PMID 30518352, 2018).
Sepsis (2 papers, 2022 to 2023). Sepsis is defined as life-threatening organ dysfunction caused by a dysregulated host response to infection. "Although Beclin1, Atg7, and Atg12 in the Sepsis group were all slightly higher than the SFP group (p < 0.05), Unc-51-like autophagy activating kinase (Ulk1), Atg5, Atg8l, and Lamp2 were not different." (PMID 37106730, 2023). "Apart from these proteins, expression of ATG12 was found to be increased in sepsis (p = 0.047), though another autophagy gene ATG5 was increased but not significant in sepsis." (PMID 35681439, 2022).
vitiligo (2 papers, 2022). Generalized well circumscribed patches of leukoderma that are generally distributed over symmetric body locations and is due to autoimmune destruction of melanocytes. "In response to oxidative stress, vitiligo melanocytes also display a reduced gene expression of ATG5 and ATG12, whose lower levels are caused by a deficiency in the expression of their transcription factor HSF-1." (PMID 36230960, 2022).
aneurysm (1 paper, 2019). Bulging or ballooning in an area of an artery secondary to arterial wall weakening. "It would be interesting to postulate whether cell‐specific removal of key autophagy factors, such as ATG5, ATG6 or ATG12, would result in a phenotype unique to aneurysm disease." (PMID 31025534, 2019).
Arthritis (1 paper, 2022). Inflammation of a joint. "WJR significantly reduced toe swelling, arthritis scores, and expression of miRNA-146a and autophagy genes (ATG5, ATG7, ATG12, Beclin1, LC32, and Bcl2)." (PMID 36440364, 2022). "We noted that treatment of the rat model with WJR resulted in a significant reduction in toe swelling, arthritis severity, expression of miRNA-146a, and expression of autophagy genes (ATG5, ATG7, ATG12, Beclin1, LC32, and Bcl2)." (PMID 36440364, 2022).
asthma (1 paper, 2020). "Previous studies have shown that ATG5 is involved in the autophagosome formation, which would form complex with ATG12 and ATG16L1, in patients with refractory asthma." (PMID 33643037, 2020).
blastoma (1 paper, 2015). A malignant neoplasm composed of undifferentiated cells. "While ATG3, ATG5, ATG7 and ATG12 are upregulated to induce autophagy in neuro-blastoma cells when G9a is inhibited." (PMID 26397365, 2015).
brain tumor (1 paper, 2023). "To assess the autophagy signal induced by IC50 doses of TMZ and EP in U87 or U87-R brain tumor cell lines, we investigated expression of autophagy pathway genes in the ULK/BECLIN1, ATG12/ATG7, and ATG3/ LC-II/autophagasome axes." (PMID 36660193, 2023).
chronic myeloid leukemia (1 paper, 2022). "OIP5-AS1 increased cell resistance to imatinib via targeting miR-30e-5p and ATG12 in chronic myeloid leukemia cells." (PMID 35756672, 2022).
co-infection (1 paper, 2016). "Although no significant changes were detected for these genes, there was a noteworthy increase in Beclin1/ATG6 and ATG12 expression during co-infection, which was not seen in Mtb single infected hMDMs even when stimulated with Torin1." (PMID 27302320, 2016).
COVID-19 (1 paper, 2022). A disease caused by infection with severe acute respiratory syndrome coronavirus 2. "MiRNAs that were downregulated in serum of COVID-19 patients mainly target genes promoting angiogenesis (e.g., VEGFA, ANGPT2, COL4A1, FGF2, ZEB1), apoptosis, autophagy, stress response (e.g., ATG12, ATG14, ATG2B, SOD2, TXNIP), and inflammation (e.g., CXCL9, CXCL10, IL1R1, TNF)." (PMID 36032130, 2022).
dermatomyositis (1 paper, 2025). Dermatomyositis (DM) is a type of idiopathic inflammatory myopathy characterized by evocative skin lesions and symmetrical proximal muscle weakness. "It was demonstrated that the expression of GRP78/BiP, an ER chaperone protein and autophagy-related 12 (ATG12) protein and Beclin-1, involved in autophagy pathways, was elevated in skeletal muscles of patients with dermatomyositis and immune-mediated necrotizing myopathy." (PMID 40943287, 2025).
E. coli infection (1 paper, 2021). "For example, RNAi knockdown of autophagy components (e.g., ATG5, ATG7, and ATG12) caused an increased pathogen load and decreased survival upon E. coli infection." (PMID 34940161, 2021).
endothelial dysfunction (1 paper, 2020). In vascular diseases, endothelial dysfunction is a systemic pathological state of the endothelium (the inner lining of blood vessels) and can be broadly defined as an imbalance between vasodilating and vasoconstricting substances produced by (or acting on) the endothelium. "Taken together, this study demonstrates that CFTR upregulation protects against PA-induced endothelial dysfunction through improving autophagic flux with an underlying mechanism being involved in enhancing Atg12-Atg5-Atg16L complex formation and restoring the CTSB and CTSD protein expression." (PMID 33123317, 2020).
gastritis (1 paper, 2023). Inflammation of the stomach. "The present study shows that ATG16L1 and ATG12 are susceptibility genes of H. pylori-infected gastritis." (PMID 37629426, 2023).
head and neck cancer (1 paper, 2022). A primary or metastatic malignant neoplasm affecting the head and neck. "ATG12 is located on chromosome 5.q, a chromosomal region frequently deleted in head and neck cancer." (PMID 34904929, 2022).
Hyperinsulinemia (1 paper, 2018). An increased concentration of insulin in the blood. "Next, we found that the expression of major components of the autophagy process, including Beclin-1, Atg7, Atg3, Atg12-Atg5, free Atg12, Atg16L1, and LC3II was not affected by hyperinsulinemia." (PMID 29719598, 2018).
intestinal obstruction (1 paper, 2024). Blockage of the normal flow of the intestinal contents within the bowel. "Down-regulation of Atg1 or Atg12 promoted intestinal excretion and mitigated the intestinal obstruction, whereas down-regulation of Atg5, or Atg7 hindered the activities of eating or defecating." (PMID 38900277, 2024). "Consistently, the groups with severe intestinal obstruction in the context of trpQ78 (that is, Atg5, Atg7 RNAi) displayed more severe apoptosis, while the Atg1 and Atg12 RNAi groups, which had mitigated intestinal obstruction, had reduced apoptosis levels." (PMID 38900277, 2024).
laryngeal carcinoma (1 paper, 2025). Carcinoma that arises from the laryngeal epithelium. "The data analysis of the TCGA‐HNSC reveals a positive correlation between the expression of CTSL and autophagy‐related markers such as ATG5, ATG7, ATG12, ATG16L and LC3b, suggesting a connection between CTSL and autophagy in laryngeal cancer." (PMID 39893643, 2025). "Analysis of the TCGA database indicates that autophagy‐related markers in laryngeal cancer tissues, such as ATG5, ATG12, ATG16L, LC3b, Beclin1, mostly exhibit an upregulation trend." (PMID 39893643, 2025).
lupus (1 paper, 2023). "The autophagy-related genes (Atg5, Atg12 and Beclin 1) were significantly upregulated in the splenic and renal macrophages in activated lymphocytes-derived DNA (ALD-DNA) induced lupus mice and in the peripheral blood mononuclear cells from SLE patients." (PMID 36865559, 2023).
lymph node metastasis (1 paper, 2021). "However, the high expression level of ATG12 but not IRS2 was correlated with OS in terms of key patient symptoms such as clinicopathological characteristics, the presence of lymph node metastasis, and degree of tumor differentiation, or whether the patient had distant metastasis." (PMID 34976838, 2021).
metastatic tumors (1 paper, 2020). "On the sections of pulmonary metastatic tumors, IF stain of Atg12 decreased in HULC siRNA group." (PMID 34766115, 2020).
Myelodysplasia (1 paper, 2025). Clonal hematopoietic stem cell disorders characterized by dysplasia (ineffective production) in one or more hematopoietic cell lineages, leading to anemia and cytopenia. "This is consistent with previous research in a murine model of myelodysplasia showing a significant decrease in the expression of p-ATG1, p-ATG6, ATG7, and ATG12." (PMID 40728989, 2025).
myocardial hypertrophy (1 paper, 2020). "Moreover, we found that the expression of other key autophagy-related genes such as ULK1, Atg12, and Atg4B, was significantly upregulated at the protein level in the left ventricle of rats with exercise-induced myocardial hypertrophy, whereas SQSTM1 (a marker of reduced autophagy) was downregulated." (PMID 32140172, 2020).
oral cancer (1 paper, 2022). "Moreover, increased expressions of Beclin-1, Atg3, Atg5, Atg7, Atg12, Atg 16, LC3-I, and LC3-II proteins indicated that 4-carbomethoxyl-10-epigyrosanoldie E triggered autophagy in oral cancer cells." (PMID 36275891, 2022).
pancreatic adenocarcinoma (1 paper, 2020). "In addition, we analysed the correlation between PTBP3, ATG12 and LC3 expression by using GEPIA, and the results indicated that PTBP3 had a strong correlation with the expression of ATG12 and LC3 in pancreatic adenocarcinoma." (PMID 31989778, 2020).
periodontitis (1 paper, 2017). An acute or chronic inflammatory process that affects the tissues that surround and support the teeth. "Specifically, there were higher protein expression levels of LC3II/I and Beclin 1, as well as increased transcriptional levels of LC3, Beclin-1, Atg7, and Atg12, in periodontal ligament stem cells isolated from patients with periodontitis compared with healthy individuals." (PMID 28690552, 2017). "The expression of autophagy-related genes (Atg12 and LC3) was shown to be positively correlated with mitochondrial ROS production in peripheral blood mononuclear cells from patients with periodontitis." (PMID 28690552, 2017).
pseudoexfoliation syndrome (1 paper, 2025). "Our study may gain importance as it is the first study in which Beclin 1, ATG5, ATG6, ATG12, p62, and LC3A/B autophagy markers are examined prospectively in the etiopathogenesis of pseudoexfoliation syndrome, comprehensively and with a control group." (PMID 40925341, 2025).
rosacea (1 paper, 2023). A chronic erythematous skin disorder that affects the face. "In the present study, we found that the mRNA expression of autophagy-related genes Becn1, Atg5, Atg10, and Atg12 was significantly increased in LL37-induced rosacea lesions after topical rapamycin treatment." (PMID 36937834, 2023). "The expression of autophagy-related genes (ATG9A, ATG10, ATG12, and PIK3C3) was evidently decreased in rosacea lesions compared with normal skin tissues in the GSE65914 dataset." (PMID 36937834, 2023).
sarcoidosis (1 paper, 2020). Sarcoidosis is a multisystemic disorder of unknown cause characterized by the formation of immune granulomas in involved organs. "For example, here, among other genes, STAT1, IL10RA, and PTEN were underexpressed in sarcoidosis CD14 monocytes compared to controls while CXCR4, ATG12, HIF1A, CCR1, and IER3 were overexpressed, consistent with the effects of TGFB1 signaling." (PMID 33363531, 2020).
schizophrenia (1 paper, 2024). A major psychotic disorder characterized by abnormalities in the perception or expression of reality. "Finally, we identified CSNK2B, TOMM40, MAP1LC3B, MFN1, CSNK2A2, PGAM5 and ATG12 as the diagnostic genes for schizophrenia." (PMID 39355378, 2024).
spinocerebellar ataxia type 7 (1 paper, 2025). "The role of ATG12 expression in spinocerebellar ataxia type 7 is introduced earlier." (PMID 40093192, 2025).
Stroke (1 paper, 2023). Sudden impairment of blood flow to a part of the brain due to occlusion or rupture of an artery to the brain. "The implication of ATG12 and ATG16L2 in the inhibition of inflammation might indicate a reduction of inflammatory responses in CE stroke, which was involved with autophagy." (PMID 37305740, 2023). "The remaining autophagy-related genes, such as ATG12, ATG16L2, ATG2B, and BECN1 were also significantly increased in CE strokes while not all types of strokes." (PMID 37305740, 2023).
cancer (52 papers, 2012 to 2025). A tumor composed of atypical neoplastic, often pleomorphic cells that invade other tissues. "Some autophagy-related genes (ATGs), such as ATG2B, ATG5, ATG9B, and ATG12, have been reported to contain frameshift mutations in cancer, implicating the potential contributions to tumorigenesis and cancer metastasis." (PMID 38338839, 2024). "Deletion of autophagy-related proteins, such as ATG4A, LC3B, and ATG12, has been associated with reduced cancer cell populations and decreased expression of vimentin, a promising marker of cancer progression." (PMID 39456967, 2024). "ATG12 is implicated in the regulation of chemoresistance via modulating autophagy in various cancers." (PMID 36624091, 2023). "Deregulating autophagy by the frameshift mutations of Atg2B, Atg5, Atg9B and Atg12 is involved in cancer development." (PMID 34829743, 2021). "Molecular mechanisms underlying Atg8 lipidation remain poorly understood despite association of Atg3, the E1 Atg7, and the composite E3 Atg12–Atg5-Atg16 with pathologies including cancers, infections and neurodegeneration." (PMID 31399562, 2019). "Moreover, several polymorphisms on the ATG12 conjugation system have also been associated with other pathologies besides cancer." (PMID 33147747, 2020). "Less specific therapeutics that disrupt or increase all ATG12 conjugation, such as those that modulate ATG12 expression levels, could cause cancer cell death due to the combined effects of both pathways." (PMID 23840208, 2013). "The association between cancer and increases in CASP3, CASP8, and ATG12/ATG5/ATG16L1 is described in the sections titled “Apoptosis”, “Exocytosis”, and “Autophagy”, respectively." (PMID 41154660, 2025). "Our experimental results from silencing both ATG12 and the enhancer are concordant with previous studies directly silencing ATG12 using small interfering RNAs in other cancer cell lines." (PMID 39018396, 2024). "Some studies demonstrate that cancer cell stemness of teratocarcinoma and ovary is reduced after knocking down ATG12, ATG7 and ATG5, indicating autophagy is a stemness promoter." (PMID 37355631, 2023). "The IRS2, IGF2, and ATG12 proteins were present mainly in cancer metabolic pathways, including the MAPK, FOXO, and RAS signaling pathways." (PMID 34976838, 2021). "Numerous studies have shown that other ATG genes, including ATG2B, ATG5, ATG9B, ATG12, and ATG16L1, are also associated with human different cancers." (PMID 34443541, 2021). "HOTAIRM1 functions as a ceRNA to regulate autophagy initiation and elongation through ULK1, ATG3, ATG7, and ATG12 in cancers." (PMID 33050642, 2020). "A number of studies on the ATG genes relevance to human cancers showed that other ATG genes are also oncogenically associated, including ATG2B, ATG5, ATG9B, ATG12 and ATG16L1." (PMID 31969156, 2020). "It was also proved that genetic silencing of Beclin1, Atg5, Atg 7, and Atg12 led to the sensitization of chemoresistant cancer cells to multiple chemotherapeutics." (PMID 32717981, 2020). "Tanshinone IIA, one of the main compounds of S. miltiorrhiza Bunge, has been shown to inhibit the growth of cancer cells via autophagy and apoptosis, which is related to the Beclin-1/Atg7/Atg12-Atg5 and PI3K/Akt/mTOR pathways." (PMID 31406500, 2019). "We also obtained similar results of the enhanced anti-cancer effects of EGFR inhibitors by suppressing the expression of ATG12." (PMID 28165387, 2017). "This study found that NORAD was activated due to an increase in oxidative stress, and this lncRNA upregulated ATG5 and ATG12 levels and may be regarded as a useful biomarker in this cancer to predict oxaliplatin resistance." (PMID 36983973, 2023). "Furthermore, the SETD2-mediated manipulation of ATG12 isoforms expression ratio in these cancer cells has an impact on their migration capability." (PMID 35585060, 2022). "Hence, ATG12 loss is associated with improved prognosis after therapy in two independent HNSCC cohorts and 7 additional cancer types." (PMID 34904929, 2022).